PPP4C (protein phosphatase 4 catalytic subunit)
Diseases named in the same sentence as PPP4C in open-access papers (continued):
Sharing a sentence is not in itself a finding about the gene and the disease.
tumor (7 papers, 2015 to 2024). "Given the significance of PPP4C in prognosis and its impact on the tumor immune microenvironment, we have devised a risk evaluation framework integrating PPP4C with genes associated with immune scoring." (PMID 39026674, 2024). "Next, the association of PPP4C expression in tumor tissues was evaluated with various clinicopathologic parameters including sex, age of diagnosis, Ann Arbor stage, ECOG, extranodal site, LDH, IPI score, B symptoms, Hans typing, and Ki-67." (PMID 38683255, 2024). "Moreover, the unbalanced transcriptional levels of PPP4C between normal and tumor tissues contributed to its high diagnostic accuracy in 14 tumor types." (PMID 37353511, 2023). "Furthermore, analysis of PPP4C expression and its clinical pathological characteristics through immunohistochemistry indicated that high PPP4C expression was linked to tumor recurrence, and patients with high PPP4C expression experienced lower DFS or OS than those with low expression." (PMID 38683255, 2024). "In both TCGA and GEO datasets, we identified higher mRNA levels of PPP4C in tumor tissues compared to normal tissues." (PMID 38683255, 2024). "Our research further explored how PPP4C expression within the tumor immune microenvironment influences LUAD prognosis." (PMID 39026674, 2024). "The findings revealed that 76.84% (146/190) of DLBCL tissues exhibited positive staining of PPP4C, primarily localized in the nucleus of tumor cells." (PMID 38683255, 2024). "In patients diagnosed with LUAD, a robust correlation has been established between the levels of PPP4C and the intricacies of the tumor microenvironment’s immune landscape." (PMID 39026674, 2024). "In recent years, researchers have shown significant interest in the connection between PPP4C and tumor." (PMID 38683255, 2024). "The data revealed a pronounced elevation of PPP4C levels in the tumor tissues compared with the normal tissues, confirmed at both protein and mRNA levels." (PMID 39026674, 2024). "Altogether, the distinct expression pattern between normal and tumor tissues, and the close correlation between PPP4C and OS indicate that PPP4C is a potential biomarker for tumorigenesis." (PMID 37353511, 2023). "With the cohort study of TCGA and GTEx, we compared PPP4C transcription levels between 33 tumor and normal tissues." (PMID 37353511, 2023). "In both X. laevis embryos and certain tumor tissues, PPP4C levels significantly correlated with canonical Wnt activation." (PMID 37353511, 2023). "Gene Set Enrichment Analysis (GSEA) of the DEGs presented a significant correlation between PPP4C and canonical Wnt activation in nine tumor types." (PMID 37353511, 2023). "To uncover PPP4C-related BPs in tumorigenesis, we analyzed the DEGs between PPP4C high (50%–100%) and low (0%–50%) expression tissues in each tumor." (PMID 37353511, 2023). "The involvement of PPP4C in LUAD is deeply intertwined with the tumor’s immune microenvironment." (PMID 39026674, 2024). "Moreover, an exploration into the nexus between PPP4C gene expression and the tumor’s immune milieu was conducted." (PMID 39026674, 2024). "PPP4C’s over-expression is associated with negative clinical outcomes, promoting both tumor proliferation and spread." (PMID 39026674, 2024). "Given the fundamental function of Wnt in AP and DV pattern specification, and the correlation between PPP4C and pattern specification in certain tumor types, we explored the relationship between PPP4C and canonical Wnt activation through GSEA of DEGs in these tumors." (PMID 37353511, 2023). "Besides, in 26 out of 33 tumor types, either high or low, PPP4C were significantly correlated with synaptic or synapse-related DEGs." (PMID 37353511, 2023). "In both datasets, PPP4C expression was greater in DLBCL tumor tissues rather than normal tissues." (PMID 38683255, 2024).
neurodevelopmental disorder (1 paper, 2020). A behavioral and cognitive disorder with onset during the developmental period that involves impaired or aberrant development of intellectual, motor, or social functions. "Hypomethylation of PPP4C may result in abnormal cortical development, increasing the risk of neurodevelopmental disorders." (PMID 32850550, 2020).
PPP4C also shares sentences with these, for which no sentence is quoted: colorectal cancer (3 papers); leukemia (2); pancreatic adenocarcinoma (2); pancreatic ductal adenocarcinoma (2); thymoma (2); acute myeloid leukemia (1); adrenocortical carcinoma (1); bladder urothelial carcinoma (1); cervical squamous cell carcinoma (1); cholangiocarcinoma (1); colon adenocarcinoma (1); colon cancer (1); dilated cardiomyopathy (1); endocervical adenocarcinoma (1); esophageal carcinoma (1); female infertility (1); glioblastoma multiforme (1); head and neck squamous cell carcinoma (1); hemorrhage (1); Insulin resistance (1); ischemic cardiomyopathy (1); Lissencephaly (1); lung squamous cell carcinoma (1); lymph node metastasis (1); lymphoid neoplasm (1); medulloblastoma (1); mesothelioma (1); myocardial hypertrophy (1); ovarian serous cystadenocarcinoma (1); paraganglioma (1).
A further 11 diseases each share a sentence with PPP4C in 1 paper.